APOA1 (apolipoprotein A1)
Description:
Participates in the reverse transport of cholesterol from tissues to the liver for excretion by promoting cholesterol efflux from tissues and by acting as a cofactor for the lecithin cholesterol acyltransferase (LCAT). As part of the SPAP complex, activates spermatozoa motility.
Synonyms: AMYLD3; HPALP2; apo(a)
Tractability: Small molecule: a structure with a bound ligand is known; it has a binding pocket of medium quality. Antibody: its Gene Ontology location is reachable by antibodies, with high confidence; UniProt places it where antibodies can reach, with medium confidence; UniProt predicts a signal peptide or a membrane-spanning region. PROTAC: ubiquitination databases record sites on it; its protein half-life has been measured.
Gene: Protein-coding gene on chromosome 11 (116,835,750 to 116,838,203, reverse strand). Ensembl gene ENSG00000118137.
Subcellular location: Secreted
Subcellular location (Human Protein Atlas): Vesicles; Cytosol; Predicted to be secreted
Pathways (Reactome):
Transport of small molecules: ABC transporters in lipid homeostasis; Chylomicron assembly; Chylomicron remodeling; HDL assembly; HDL clearance; HDL remodeling
Disease: Defective ABCA1 causes TGD; Dengue Virus-Host Interactions; Dengue virus activates/modulates innate and adaptive immune responses; Maturation of DENV proteins
Metabolism of proteins: Amyloid fiber formation; Post-translational protein phosphorylation; Regulation of Insulin-like Growth Factor (IGF) transport and uptake by Insulin-like Growth Factor Binding Proteins (IGFBPs)
Vesicle-mediated transport: Scavenging by Class A Receptors; Scavenging by Class B Receptors; Scavenging of heme from plasma
Cellular responses to stimuli: Heme signaling
Hemostasis: Platelet degranulation
Metabolism: PPARA activates gene expression
Sensory Perception: Retinoid metabolism and transport
Gene Ontology:
Molecular function: amyloid-beta binding; apolipoprotein A-I receptor binding; apolipoprotein receptor binding; chemorepellent activity; cholesterol binding; cholesterol transfer activity; enzyme binding; heat shock protein binding; high-density lipoprotein particle receptor binding; identical protein binding; phosphatidylcholine-sterol O-acyltransferase activator activity; phospholipid binding; protein binding; receptor ligand activity; signaling receptor binding; protein homodimerization activity; high-density lipoprotein particle binding; lipid binding; lipid transporter activity; lipoprotein particle binding
Biological process: amyloid-beta formation; cellular response to lipoprotein particle stimulus; cholesterol efflux; cholesterol homeostasis; cholesterol import; cholesterol metabolic process; cholesterol transport; ERK1 and ERK2 cascade; G protein-coupled receptor signaling pathway; high-density lipoprotein particle assembly; high-density lipoprotein particle remodeling; integrin-mediated signaling pathway; negative chemotaxis; negative regulation of cell adhesion molecule production; negative regulation of cytokine production involved in immune response; negative regulation of heterotypic cell-cell adhesion; negative regulation of inflammatory response; negative regulation of interleukin-1 beta production; negative regulation of response to cytokine stimulus; negative regulation of tumor necrosis factor-mediated signaling pathway; negative regulation of very-low-density lipoprotein particle remodeling; peptidyl-methionine modification; phosphatidylcholine biosynthetic process; phospholipid efflux; phospholipid homeostasis; and 18 more
Cellular component: blood microparticle; cytoplasmic vesicle; endocytic vesicle; extracellular exosome; extracellular region; extracellular vesicle; high-density lipoprotein particle; spherical high-density lipoprotein particle; very-low-density lipoprotein particle; chylomicron; cytosol; early endosome; endocytic vesicle lumen; endoplasmic reticulum lumen; low-density lipoprotein particle; plasma membrane; secretory granule lumen
Genetic constraint (gnomAD): Loss-of-function variants: 22 observed, 26.9 expected, observed/expected ratio (o/e) 0.82, 90% interval 0.58 to 1.17. The upper end of that interval is the gene's LOEUF score, 1.17, which puts it in group 5 of 6, group 1 being the genes least tolerant of losing a copy. Missense variants: 351 observed, 366.84 expected, observed/expected ratio (o/e) 0.96, 90% interval 0.88 to 1.04. Synonymous variants: 163 observed, 158.88 expected, observed/expected ratio (o/e) 1.03, 90% interval 0.9 to 1.17.
Homologues: Orthologues: chimpanzee APOA1 (100% identical), macaque APOA1 (95% identical), dog APOA1 (85% identical), rabbit APOA1 (80% identical), mouse Apoa1 (65% identical), pig APOA1 (64% identical), guinea pig APOA1 (63% identical), rat Apoa1 (63% identical), tropical clawed frog apoa1 (39% identical), zebrafish apoa1a (25% identical), zebrafish apoa1b (21% identical). Paralogues in human: APOA4 (25% identical), APOA5 (24% identical), APOE (20% identical).
Diseases named in the same sentence as APOA1 in open-access papers:
APOA1 is named in the same sentence as 554 diseases in open-access papers, as found by Europe PMC text mining. Sharing a sentence is not in itself a finding about the gene and the disease. The quoted sentences say what the papers report.
atherosclerosis (376 papers, 2005 to 2026). A disease characterized by the build-up of fatty material and calcium deposition in the arterial wall resulting in partial or complete occlusion of the arterial lumen. "Our findings suggest Bim in myeloid cells as a potential target for inhibition to protect against atherosclerosis development in the context of ApoA1 deficiency." (PMID 40120762, 2025). "Accordingly, with the progression of CHB disease, the risk of atherosclerosis can be lowered, and the ApoB/ApoA1 ratio can be down-regulated." (PMID 38744926, 2024). "A higher ApoB/ApoA1 ratio is associated with an increased risk of atherosclerosis and myocardial infarction, making it a valuable marker in the prediction and management of cardiovascular events." (PMID 39273041, 2024). "In the case of late-stage atherosclerosis, the administration of apoA1 caused a very modest impact on the volume of atherosclerosis lesions and on plaque structure." (PMID 36979690, 2023). "Since the ApoB/ApoA1 ratio was suggested as a clinical index for atherosclerosis, few GWASs have investigated the phenotypes associated with it." (PMID 36140721, 2022). "Indicating the presence of atherosclerosis, ApoA1 is also a prognostic parameter of an increased risk of neurovascular events." (PMID 35054033, 2022). "ApoA1 and apoB were the two major sources of apolipoproteins involved in lipid transport and were proven to function in the procession causing atherosclerosis and its complications." (PMID 36713523, 2022). "It is important to note that CD4+ T-cells in patients with a high ApoB:ApoA1 ratio showed increased response to oxidative stress signalling, a process that has been implicated in atherosclerosis through oxidization of LDL and altered inflammatory processes." (PMID 33640328, 2021). "ApoB and apoA1 are major apolipoproteins involved in lipid transport and the pathogenic processes and complications of atherosclerosis." (PMID 33774330, 2021). "The Cardiovascular Risk in Young Finns Study shows that elevated ApoB and ApoB:ApoA1 ratio and reduced ApoA1 in children and adolescents reflects a predisposition to subclinical atherosclerosis in adulthood in healthy individuals." (PMID 33640328, 2021). "The obtained results were correlated with the expression level of platelet and megakaryocyte transcripts for APOA1 and A2M genes encoding atherosclerosis biomarkers: apolipoprotein A1 (ApoA1) and α-2-macroglobulin (α2M), respectively." (PMID 33086557, 2020). "Several biomarkers and atherosclerosis imaging measures have been evaluated for association with an incident of cardiovascular disease, including apolipoprotein A1 (ApoA1) and α-2-macroglobulin (α2M)." (PMID 33086557, 2020). "Lower ApoA1 has been reported to be statistically significant associations with high-risk atherosclerosis." (PMID 32874784, 2020). "When administered to mouse models of atherosclerosis, anti-apoA-1 IgG enhanced atherogenesis, myocardial necrosis and premature death indicating that anti-apoA-1 IgG have the potential to serve as a causative biomarker for CVD." (PMID 31261925, 2019). "HDL-C has also been primarily associated with a protein, apolipoprotein A-I (APOA1) and the over-expression of APOA1 has equally been found to reduce atherosclerosis in mice." (PMID 30509298, 2018). "Periodontal microbiome infection is associated with significant decreases in Apoa1, Apob, Birc3, Fga, FgB genes that are associated with atherosclerosis." (PMID 26619277, 2015). "Diabetes and atherosclerosis are associated with disorders of lipids and lipoproteins, notably high apolipoprotein B (apoB) and low apolipoprotein A1 (apoA1) are well established." (PMID 25318463, 2014).
atherosclerosis (continued). "The association of diabetes and atherosclerosis with disorders of lipids and lipoproteins, notably high apolipoprotein B (apoB) and low apolipoprotein A1(apoA1) is well established." (PMID 22811893, 2012). "Moreover, high ApoB/ApoA1 levels were associated with subclinical atherosclerosis and unstable plaque disease." (PMID 38310324, 2024). "Studying the protective effects linked to APOA1 could reveal new methods to mitigate the risk of myocardial infarction and atherosclerosis, especially since astronauts endure above-average radiation exposure." (PMID 39039045, 2024). "Furthermore, ApoA1 and GlycA were differentially associated with disease activity and serological measures, as well as atherosclerosis incidence and myocardial infarction mortality risk through disease-wide association." (PMID 38048621, 2024). "In the current study, we tested whether the virtual absence of HDL due to a genetic deficiency in hepatocyte-derived APOA1 alters bone marrow functionality and thereby changes the immune status and atherosclerosis susceptibility of mice." (PMID 34698355, 2022). "Moreover, the ApoB/ApoA1 ratio was associated with femoral artery atherosclerosis as measured both as intima-media thickness and plaque occurrence; and carotid artery atherosclerosis measured by intima-media thickness." (PMID 34996506, 2022). "To verify the potential effect of the APOA1/HDL deficiency-associated changes in bone marrow functionality on atherosclerosis susceptibility, we transplanted bone marrow from APOA1 KO mice and WT controls into atherosclerosis-prone, hypercholesterolemic LDL receptor KO mice." (PMID 34698355, 2022). "Studies have shown that ApoA1 mimetic peptides may ameliorate nephropathy in a mouse model of atherosclerosis, such as ApoE-deficient mice." (PMID 35629966, 2022). "Indeed, increasing the expression of the apoA-1 gene in ApoE-deficient mice markedly suppressed atherosclerosis." (PMID 34202121, 2021). "Similarly, ApoA1 has been observed to be equivalent or better than HDL-C as a risk marker for cardiovascular or atherosclerosis events." (PMID 33794863, 2021). "According to previous studies, lower ApoA1 may have positive effect on atherosclerosis or high-risk plaque features, which is exactly in contradiction to our results." (PMID 32874784, 2020). "Elevated APOA1 levels are strongly associated with a reduced risk of cardiovascular events in patients, and a damaging mutation in APOA1 confers an increased risk of atherosclerosis." (PMID 32566106, 2020). "We speculate that the decreased level of apolipoprotein A1 in patients with epilepsy may indicate abnormal lipid metabolism and high risk of atherosclerosis." (PMID 33082886, 2020). "The ApoB/ApoA1 ratio is linked to early atherosclerosis as well." (PMID 32717783, 2020). "Interestingly, SAA has also been suggested to be responsible for the low HDL cholesterol and apoA1 levels observed in patients with active sarcoidosis, which has been linked to an increased risk of atherosclerosis in sarcoidosis patients." (PMID 31681260, 2019). "Accordingly, analysis of specialized lipid parameters showed statistically significant increase in the ApoB/ ApoA1 ratio which associated with the development of clinical cardiovascular disease and with early atherosclerosis onset; moreover is considered the stronger predictor of vascular events." (PMID 28806974, 2017). "A plasma concentration of 50 mM of caffeine, which is equal to the average plasma caffeine concentration of healthy individuals who consume coffee, may decrease the risk of atherosclerosis by increasing liver ApoA1 and PON1 protein levels." (PMID 29215336, 2017). "According to our results, caffeine may reduce atherosclerosis risk by increasing liver ApoA1 and PON1 protein levels." (PMID 29215336, 2017). "Low ratio of ApoA1 to ApoB reflects the potential risk of atherosclerosis." (PMID 24160749, 2013).
atherosclerosis (continued). "Administration of purified APOA1 to mice, as well as induction of human APOA1 gene overexpression through transgenic or adenoviral approaches, has been shown to attenuate atherosclerosis." (PMID 40371638, 2025). "Apolipoprotein A1 (Apo-A1) is the primary structural protein of HDL-C particles, and its elevated level is correlated with a lower risk of atherosclerosis." (PMID 40036186, 2025). "APOA1, the primary apolipoprotein component of HDL, plays a direct role in cholesterol efflux in the brain and is strongly linked to atherosclerosis and dementia." (PMID 40739302, 2025). "HDL-C inhibits atherosclerosis by removing cholesterol from the vascular wall through reverse cholesterol transport, while apoA1, as the primary structural protein of HDL, shares a similar mechanism in reducing the risk of atherosclerosis." (PMID 41235335, 2025). "In this study, we constructed an innovative inorganic–organic hybrid nanosystem, enhanced with apolipoprotein ApoA1, to address atherosclerosis (AS) from dual perspectives and optimize the clearance of lipid plaques." (PMID 40076117, 2025). "Considering the observation that ALK1- and SR-B1-mediated LDL transcytosis are necessary for the formation of atherosclerosis, we propose that an additional mechanism by which APOA1 and HDL are beneficial is by the continuous competitive binding to SR-B1." (PMID 38479648, 2024). "The authors put hamsters on a high-cholesterol/high-fat diet to assessthe association between APOC3 and atherosclerosis and observed reducedlevels of TG, total cholesterol, ApoB, and ApoE and enhancedlevels of HDL-C and ApoA1." (PMID 39228490, 2024). "Although most studies have focused on the role of ApoA1 in atherosclerosis and cardiovascular disease, some studies have revealed relatively lower levels of serum ApoA1 in patients with various cancers, including breast cancer." (PMID 38566092, 2024). "They found that the sensitivity of predicting MACE in the 3-month follow-up period with the ApoB/ApoA1 ratio was 84%, and the specificity of predicting the number of atherosclerosis vessels in the 1-year follow-up period was 81%." (PMID 38310324, 2024). "Study showed that expressing APOA2 and APOA1 are more vulnerable to suffering from atherosclerosis than those expressing APOA1 alone in mice." (PMID 38177949, 2024). "ATP-binding cholesterol transporters ABCG1 and ABCA1 export cholesterol from macrophages in the vessel wall to HDL and ApoA-1, reducing lipid deposition and preventing foam cell formation, thereby attenuating atherosclerosis (Ouimet, Barrett & Fisher, 2019)." (PMID 39421410, 2024). "Future research should explore additional lipid indicators, such as apolipoprotein A1 and apolipoprotein B, to gain a more comprehensive understanding of lipid metabolism in relation to frailty and atherosclerosis." (PMID 38781179, 2024). "APOA1-Milano patients are protected from atherosclerosis, yet the mechanism for this protection is unclear." (PMID 38479648, 2024). "Studies have shown that regulating APOA1 transcription and increasing APOA1 levels in mice can reduce atherosclerosis." (PMID 38957396, 2024). "Concurrently, several studies indicate that the ratio of ApoB/ApoA1 can reflect the cholesterol balance between atherosclerosis and anti-atherosclerotic lipoprotein particles, and can better predict cardiovascular risk." (PMID 38310324, 2024). "The results of human apoA1 injection in apoE-/- cholesterol-fed mice with early-stage atherosclerosis differed from those of mice with an advanced stage." (PMID 36979690, 2023). "This seems to be even more likely given that in the available literature data, the deletion of the ApoA1 gene in mice contributed to a greater incidence of atherosclerosis independently of plasma HDL-C content." (PMID 37686357, 2023).